HCN2 (hyperpolarization activated cyclic nucleotide gated potassium and sodium channel 2)
Diseases named in the same sentence as HCN2 in open-access papers (continued):
Sharing a sentence is not in itself a finding about the gene and the disease.
absence seizures (7 papers, 2012 to 2022). "Given that HCN1-/- mice show enhanced seizure susceptibility and that HCN2-/- mice suffer from absence seizures, we next focused our investigations on the alteration of Ih currents associated with HCN channels in EC layer II in X11-/-/X11L-/- mice." (PMID 23034178, 2012). "The HCN2-null mouse demonstrates a complete loss of the Ih current in thalamocortical relay neurons, leading to increased neuronal hyperexcitability (spontaneous absence seizures) and dysrhythmia." (PMID 35663267, 2022). "Moreover, kainic acid-induced seizure susceptibility is increased in HCN1-/- mice, and HCN2-deficient mice exhibit spontaneous absence seizures." (PMID 23034178, 2012). "Additionally, loss of function in HCN2 and loss of TRIP8b protein (an auxiliary protein to HCN channels) can lead to the emergence of spontaneous absence seizures." (PMID 34149352, 2021). "Similarly, another mouse strain displaying a spontaneous mutation in the HCN-2 gene, resulting in an ∼90 % knockdown of HCN-2 mRNA, displays spontaneous absence seizures, as well as occasional tonic–clonic seizures." (PMID 24953239, 2015). "The hypothesis that a parallel reduction of Ih in cortical and thalamic areas can lead to absence epilepsies, is supported by the fact that genetic and spontaneous HCN2 knock-out mouse develops spontaneous absence seizures." (PMID 26578877, 2015). "The HCN2 cases with GOF variants according to the electrophysiological studies performed on oocytes from Xenopus laevis include the inherited p.S632W variant as observed in 2 cases with idiopathic photosensitive occipital epilepsy, 1 case with febrile seizures, and 1 case with absence seizures." (PMID 35663267, 2022). "In the VB nucleus, loss of HCN2, but not HCN4, alters underlying thalamic oscillations, thereby causing absence seizures." (PMID 34149352, 2021). "The preserved Ih in these cells may partially explain the infrequent absence seizures and short bursts of activity in our LFP recordings in TRIP8b−/− mice, as compared to the severe epileptic phenotype of HCN2 knockouts." (PMID 29168010, 2018).
Arrhythmia (7 papers, 2013 to 2024). Any cardiac rhythm other than the normal sinus rhythm. "Male, but not female, CIH rats have altered expression of Cav3, Cacna1c, Cacnb2, Kcne5, Kcnd2, and Hcn2 which may preferentially predispose postnatal males to develop arrhythmia." (PMID 38981849, 2024). "In mice, loss of HCN2 leads to cardiac dysrhythmias, persistent spike-wave discharges similar to those seen in absence epilepsy, ataxia, tremor, reduced neuropathic and inflammatory pain, antidepressant-like behavior, infertility, and severely restricted growth." (PMID 29466436, 2018). "Moreover, cardiac‐specific overexpression of HCN2 in mice (HCN2‐Tg) made hearts highly susceptible to arrhythmias induced by chronic β‐adrenergic stimulation." (PMID 23709563, 2013). "Indeed, in an earlier study, we showed that activation of sympathetic activity contributes to sudden death in dnNRSF‐Tg mice;14 moreover, our present findings show that HCN2‐Tg mice are highly susceptible to isoproterenol‐induced arrhythmias." (PMID 23709563, 2013). "In the present study, we demonstrated that HCN2-overexpressing ventricular myocytes showed a higher vulnerability to arrhythmia even under mild, commonly observed hypokalemic conditions." (PMID 31087220, 2019). "Electrophysiological remodeling, i.e., reactivation of fetal cardiac genes, including T-type Ca2+ channel and hyperpolarization-activated, cyclic nucleotide-sensitive (HCN) cation channels (HCN2 and -4) have also been reported to increase the vulnerability to arrhythmia." (PMID 31087220, 2019). "Thus increased expression of ventricular HCN2 channels appears to promote susceptibility to isoproterenol‐induced cardiac arrhythmias without affecting cardiac structure or function." (PMID 23709563, 2013). "Lethal arrhythmias, such as ventricular tachycardia (VT) or ventricular fibrillation (VF) were observed in neither the WT (n = 0 of 11) nor the HCN2-Tg (n = 0 of 10) mice." (PMID 31087220, 2019). "Although alteration in the expression of HCN2 has not been related to arrhythmias in physiological conditions, under pathological conditions HCN2 overexpression induces arrhythmias, which is consistent with higher expression levels of HCN2, therefore suggesting that HCN2 might play a role in ACM." (PMID 39200271, 2024).
depression (7 papers, 2014 to 2024). "HCN1 and HCN2 were reported to be highly expressed in brain regions known to be involved in the pathophysiology of major depression, namely prefrontal cortex, hippocampus, ventral tegmental area (VTA) and nucleus accumbens (NAc)." (PMID 34858192, 2021). "Decreased expression and function of the hyperpolarization-activated cyclic nucleotide-gated channel 2 (HCN2) occurs in the ChIs of the NAc shell in mouse models of depression with p11 conditional knockout (cKO) mice and SDS mice." (PMID 32694984, 2020). "Similarly, genetic ablation of Trip8b, an auxiliary protein that regulates HCN1 and HCN2 expression, also increases resistance to depression." (PMID 39434909, 2024). "Effects of modulating HCN2 expression and function on depression-like behavior." (PMID 34858192, 2021). "Although clinical studies are limited, we can presume that CHT, HCN2, GSK3β, and p11 may be important targets for the treatment of comorbid addiction and depression in the future owing to the findings from preclinical studies." (PMID 32694984, 2020). "Intriguingly, the role of HCN2 and HCN4 in major depressive disorder is less straightforward than HCN1." (PMID 39434909, 2024). "Selective knockdown of HCN2 in VTA DA neurons by shRNA increased anxiety-like and depression-like behaviors." (PMID 34858192, 2021).
breast carcinoma (6 papers, 2021 to 2025). "We found that HCN2 and HCN3 are overexpressed in breast cancer cells compared with normal breast epithelia, and the high expression of HCN2 and HCN3 is associated with poorer survival in breast cancer patients." (PMID 34841695, 2021). "Western blot employed to determine the expression of endogenous HCN2, HCN3, BRCA1, BRCA2, and RAD51, confirmed that either HCN2 or HCN3 was overexpressed in the breast cancer cells, whilst HEK293 had low expression in both of HCN2 and HCN3." (PMID 40764992, 2025). "HCN channels, particularly HCN2 and HCN3, are overexpressed in breast cancer and associated with poor survival outcomes." (PMID 40764992, 2025). "From the analysis of 316 breast cancer cases, those cases which showed both high HCN2 and HCN3 expression were most frequently of the TNBC subtype (68.4%), prompting us to focus our study on TNBC." (PMID 34841695, 2021). "Since breast cancer cells showed increased expression of both HCN2 and HCN3, we investigated the significance of each to ER‐stress." (PMID 34841695, 2021). "Here, we found that low expression of NEIL3, CDC25C, and NEK2 predicted high RFS and OS respectively (p < 0.05), and low expression of HCN2 predicted high OS (p < 0.05) in all breast cancer." (PMID 33644115, 2021). "Hence IVA can be used with PARP, specifically for breast cancers that express HCN2/HCN3 to induce synergistic effect." (PMID 40764992, 2025). "According to the existing literature, except for NEK2 the expression and prognostic significance of the NEIL3, CDC25C, and HCN2 genes are still unknown in breast cancer." (PMID 33644115, 2021). "Interestingly, we find elevated Notch FL levels upon HCN2 depletion in three different types of breast cancer cell lines, including CAL-51, a triple negative cell type, suggesting that indirect regulation of Notch processing by HCN2 might apply to many situations in breast tissue." (PMID 39663000, 2025). "Two other members of the HCN family, HCN2 and HCN3, were shown to be overexpressed in clinical breast cancer and to have adverse prognostic significance; they were also predictive markers for ivabradine response in in vitro breast cancer models." (PMID 37239316, 2023). "Six of these genes (MUM1, AC016876.1, PLK5, HCN2, OAZ1, AC027307.2) have been identified as prognostic features for many cancers, such as colorectal cancer, breast cancer, non-small cell lung cancer." (PMID 36304471, 2022). "Using immunohistochemistry to examine HCN2 and HCN3 protein expression of primary breast cancer in tissue microarray, we confirmed that HCN2 and HCN3 were significantly upregulated in tumour compared with normal breast epithelia." (PMID 34841695, 2021). "Further in vivo support of this oncogenic effect is reflected in our HCN2 and HCN3 expression in over 200 primary breast cancers which showed a significant correlation with poorer survival." (PMID 34841695, 2021). "Overexpression of HCN2 and HCN3 proteins was consistently found in breast cancer cells, with BT474 and TNBC cells MDA‐MB‐231, MDA‐MB‐453 showing the most significant upregulation." (PMID 34841695, 2021). "On contrast, IVA induces ER stress in breast cancer cells with increased HCN2/HCN3 expression, which is not found in non-neoplastic cell line HEK293." (PMID 40764992, 2025). "IVA treatment led to significant reduction of RAD51-EGFP signals in all 5 breast cancer cell lines that overexpressed HCN2 or HCN3, but not in HEK293." (PMID 40764992, 2025). "We found both HCN2 and HCN3 were predominantly localized to the cell membrane, suggesting that HCN2 and HCN3 could be functionally important in breast cancer cells." (PMID 34841695, 2021). "Based on our results, only HCN2 and HCN3 are overexpressed in breast cancer." (PMID 34841695, 2021). "In the current study, we found HCN2 and HCN3 are overexpressed in breast cancer cells." (PMID 34841695, 2021).
breast carcinoma (continued). "In all breast cancer, low expression of NEIL3, CDC25C and NEK2 predicted high RFS (p < 0.05) respectively, while high expression of HCN2 predicted high RFS (p < 0.05), and low expression of NEIL3, CDC25C, NEK2 and HCN2 predicted high OS respectively (p < 0.05)." (PMID 33644115, 2021). "To test whether PTPN23, HCN2, or SGK3 affect Notch levels in breast cancer cells, we first evaluated by Western blot the levels of NOTCH1-3 in a panel of five breast cancer lines of different origin." (PMID 39663000, 2025).
cardiac hypertrophy (5 papers, 2017 to 2021). "In the present study, the selective upregulation of Hcn1 gene is consistent with previous studies using a mouse model of cardiac hypertrophy, although Hcn2 and Hcn4 are more abundant than Hcn150." (PMID 34489488, 2021). "As a main result we found that AGAT−/− mice exhibited altered gene expression related to energy metabolism (Fbp2, Ucp2), cardiac hypertrophy and fibrosis (Nppa, Ctgf), immune response (Fgl2), and the conduction system of the heart (Dsc2, Ehd4, Hcn2, Hcn4, Scn4a, Scn4b)." (PMID 32179820, 2020). "Still, mRNA levels of Hcn2, β2-adrenergic receptor, and Bnf, a thyroid hormone-dependent ventricular hypertrophy marker, were raised, along with severe bradycardia, concluding that thyrotoxicosis may have pathological consequences that could continue ahead of the serum T4 level recovery." (PMID 28791308, 2017). "Sp1 can potentially promote cardiac hypertrophy by activating the transcription of a panel of hypertrophic genes, including troponin T, ANF, HCN2/4, and SERCA2." (PMID 33015041, 2020).
Cognitive impairment (4 papers, 2019 to 2023). Abnormal cognition is characterized by deficits in thinking, reasoning, or remembering. "Therefore, an age-related decrease of HCN1 and HCN2 protein expression in the aged hippocampus might be related to age-dependent cognitive impairment, alterations of long-term potentiation, and synaptic transmission." (PMID 32128096, 2019).
heart failure (4 papers, 2017 to 2021). Inability of the heart to pump blood at an adequate rate to meet tissue metabolic requirements. "High expression of Hcn2 and Hcn3 are associated to cause sinoatrial node dysfunction ultimately leading to heart failure." (PMID 32673370, 2020). "Additionally, in a mouse model of heart failure, cardiac-specific overexpression of HCN2 in mice (HCN2-Tg) made hearts highly susceptible to arrhythmias induced by chronic β2-adrenergic stimulation." (PMID 34835334, 2021). "For example, HCN2 and HCN4 channels are upregulated in heart failure, giving rise to potentially lethal arrhythmias." (PMID 32948209, 2020). "Despite this absence of miR-dependent regulation of HCN2/4 in heart failure, some mechanistic role of HCN2/4 has been nonetheless attributed to hypertrophy and tachycardia." (PMID 28666417, 2017).
neuropathy (4 papers, 2015 to 2025). A disorder affecting the nervous system that manifests with pain, tingling, numbness, and/or muscle weakness. "In the current study, we used a neuropathy rat model induced by chronic constriction injury (CCI) of sciatic nerve to evaluate the change of expression of HCN1/HCN2 mRNA in peripheral nerve and spinal cord." (PMID 27901476, 2017). "A selective HCN2 blocker might also be promising, particularly for the treatment of chronic pain conditions including neuropathy and inflammation." (PMID 25580535, 2015). "We could largely confirm these results in a different model of neuropathy using a virtually identical HCN2 mutant (snsHCN2KO)." (PMID 25580535, 2015). "Our study revealed the change of expression of HCN1/HCN2 mRNA in the left/right sciatic nerve, left/right dorsal root ganglion (DRG) and spinal cord after CCI induced neuropathy." (PMID 27901476, 2017). "In the left sciatic nerve where neuropathy was induced by CCI, the expression of HCN1/HCN2 mRNA decreased." (PMID 27901476, 2017). "We explore whether PEMF have a therapeutic effect in CCI induced neuropathy and whether there is a change in the expression of HCN1/HCN2 after PEMF therapy." (PMID 27901476, 2017). "In other regions (LD: left dorsal root ganglion, SP: spinal cord, RD: right dorsal root ganglion, RN: right sciatic nerve) of nerves where no neuropathy was induced, no change of HCN1/HCN2 mRNA was observed." (PMID 27901476, 2017).
Parkinson disease (4 papers, 2016 to 2025). A progressive degenerative disorder of the central nervous system characterized by loss of dopamine producing neurons in the substantia nigra and the presence of Lewy bodies in the substantia nigra and locus coeruleus. "We quantified methylation of 2 identified regions at adjacent genes (HCN2 and NEFM) known to increase the risk for Parkinson’s disease and observed significant hypomethylation." (PMID 32178731, 2020). "Aberrant SUMOylation has been linked to neurological diseases that also display alterations in HCN1 and HCN2 channel expression, such as seizures and Parkinson’s disease." (PMID 28127275, 2016). "Both HCN2 and NEFM are regionally expressed in Parkinson’s disease tissues and their function has a critical role in neuronal plasticity and survival detailed in “Discussion” section." (PMID 32178731, 2020). "In our previous work, we characterized non-germline ASMs in the mouse genome at two genes, Hcn2 and Park7, with potential in Parkinson’s disease." (PMID 32178731, 2020). "Therefore, targeting H2R and its downstream coupled HCN2 channels in EPN PV neurons and H3R in STN neurons projecting to the EPN may represent potential therapeutic strategies for the clinical treatment of parkinsonism‐related motor dysfunction." (PMID 40013534, 2025).
Ataxia (3 papers, 2017 to 2023). Ataxia refers to impaired coordination of voluntary muscle movement. "Mice possessing a C-terminal truncated HCN2 channel possess a phenotype which is referred to as apathetic; they exhibit ataxia, generalized spike–wave absence seizures, and tonic–clonic seizures." (PMID 28286469, 2017).
migraine (3 papers, 2021 to 2026). "Multiple studies have linked migraine pathophysiology to HCNx channels, particularly HCN2." (PMID 41318467, 2025). "Based on these characteristics, HCN2 is considered a potential pharmacological target for the development of novel analgesics that are effective against neuropathic pain and migraine." (PMID 41601547, 2026).
Seizure (3 papers, 2013 to 2023). A seizure is an intermittent abnormality of nervous system physiology characterized by a transient occurrence of signs and/or symptoms due to abnormal excessive or synchronous neuronal activity in the brain. "HCN2-knockout animals have been reported to develop spontaneous absence seizures and cardiac sinus arrhythmia." (PMID 37293624, 2023).
atrioventricular block (2 papers, 2020 to 2026). A heart block that is initiated in the atrioventricular node. "Our previous work identified adenoviral gene transfer of Hcn2 and SkM1, encoding a “funny current” and skeletal fast sodium current, respectively, as a potent combination to induce short-term biological pacing in dogs with atrioventricular block." (PMID 33488393, 2020). "In a complete AV-block rat model, AAV-mediated Hcn2 expression induced robust ectopic pacemaker activity in the presence of isoproterenol, whereas TBX18 expression neither generated such activity nor augmented Hcn2-mediated pacing." (PMID 42275147, 2026).
Bradycardia (2 papers, 2020 to 2021). A slower than normal heart rate (in adults, slower than 60 beats per minute). "As a further proof of the efficacy of SkM1-based approaches, functional delivery of HCN2/SkM1 via another platform, namely human cardiomyocyte progenitor cells (CPCs), was recently demonstrated in bradycardia models." (PMID 34409019, 2021). "Altogether these studies support further development of CPC-mediated delivery of Hcn2/SkM1 and functional testing in bradycardia models." (PMID 33488393, 2020).
Cerebral ischemia (2 papers, 2013 to 2020). Restriction of arterial blood supply to the brain associated with insufficient oxygenation to support the metabolic requirements of the tissue. "Fourth, it is necessary to find an appropriate method to further investigate the effect of HCN2 channels on autophagosome and lysosome fusion in the case of cerebral ischemia in vivo." (PMID 32519067, 2020). "Based on the observation that transient arterial occlusion alters hcn2 gene expression in infarcted basal ganglia 24 h after surgery, we next investigated the functional role of HCN2 channels in vivo during experimental cerebral ischemia." (PMID 24373160, 2013). "In C57Bl/6 (wildtype, WT), hcn2+/+ and hcn2-/- mice we used an in vivo model of cerebral ischemia (transient middle cerebral artery occlusion (tMCAO)) to depict a functional impact of HCN2 in stroke formation." (PMID 24373160, 2013).
cognitive decline (2 papers, 2019 to 2024). "In parallel, western blots of the hippocampus of presymptomatic mice (4 months old) were probed with antibodies to HCN1, HCN2, and HCN3 to monitor whether changes in the expression of HCN channels occur before overt cognitive decline in Tau35 mice." (PMID 38994745, 2024).
diabetic neuropathy (2 papers, 2021 to 2023). A chronic, pathological complication associated with diabetes mellitus, where nerve damages are incurred due to diabetic microvascular injury involving small blood vessels that supply these nerves, resulting in peripheral and/or autonomic nerve dysfunction. "They found an increased level of cAMP in the somatosensory neurons of the tested animals and proposed that this is the reason why excessive HCN2 activation leads to the firing of repetitive nociceptive nerve fibers and associated effects in diabetic neuropathy pain." (PMID 37893054, 2023).
lung carcinoma (2 papers, 2014 to 2024). "Recent research has shown that staurosporine, as well as its clinically relevant analog PKC412, induces Ca2+ influx through the hyperpolarization-activated cyclic nucleotide-gated channel HCN2 in human lung cancer cells and neurons." (PMID 25037570, 2014). "These genes include GRIA3, TAF7L, ARL14, PCDHGA9, MDGA1, ZFPM2, OSR2, TMC8/TMC6, HCN2, and CDK5R2, which are likely to be relevant in human lung cancer and are also epigenetically deregulated upon exposure to ECS in our animal study." (PMID 39273313, 2024).